KRT18P55 (keratin 18 pseudogene 55)
Gene: Transcribed processed pseudogene on chromosome 17 (28,276,044 to 28,277,336, reverse strand). Ensembl gene ENSG00000265480.
Diseases named in the same sentence as KRT18P55 in open-access papers:
KRT18P55 is named in the same sentence as 2 diseases in open-access papers, as found by Europe PMC text mining. Sharing a sentence is not in itself a finding about the gene and the disease. The quoted sentences say what the papers report.
gastric cancer (1 paper, 2022). A primary or metastatic malignant neoplasm involving the stomach. "For example, lncRNAs such as HOXA-AS2, FOXD2-AS, and KRT18P55 are upregulated in gastric cancer (GC) and they are significantly associated with clinical parameters such as tumor size, lymph node metastasis and H. pillory infection, introducing them potential tumor markers for GC." (PMID 36471781, 2022).
KRT18P55 also shares sentences with these, for which no sentence is quoted: tumor (1 paper).